HIF1A (hypoxia inducible factor 1 subunit alpha)
Diseases named in the same sentence as HIF1A in open-access papers (continued):
Sharing a sentence is not in itself a finding about the gene and the disease.
colon adenocarcinoma (17 papers, 2008 to 2026). "It has been reported that the expression of CA12 has increased in human colon adenocarcinoma cells in a HIF1α-dependent manner and is necessary for tumor cell proliferation both in vivo and in vitro." (PMID 35893764, 2022). "Here we show, that murine colon adenocarcinoma cells with attenuated response to hypoxia, due to a knock-down (KD) of HIF-1α, produce smaller and less hypoxic tumors in an orthotopic mouse model when compared to tumors induced with control cells." (PMID 33142239, 2020). "According to recent studies, Nrf2 knockdown results in decreased angiogenesis in colonic adenocarcinoma cells and endothelial tube formation assays, both due to decreased expression of HIF-1α." (PMID 25340789, 2014). "Interestingly, that moderate HIF-1α expression level in Treg cells was sufficient to protect the host from MC38 colon adenocarcinoma and metastatic B16F10 invasion." (PMID 33024109, 2020). "Mouse MC-38 colon adenocarcinoma cells were exposed to normoxia (21% oxygen) or hypoxia (0.2% oxygen) for 8 to 72 hours using conventional two-dimensional (2D) dish culture, and mRNA levels of HIF-1α and HIF-2α were determined by RT-qPCR." (PMID 25978030, 2015). "Hypoxia-induced or exogenous overexpression of HIF-1α increased in vitro invasion by human colon adenocarcinoma cells, while stable normoxic overexpression of HIF-1α promoted anchorage-independent growth in melanocytes having an activated AKT signaling pathway." (PMID 19919690, 2009). "Recent studies reported that interfering treatments targeting HIF-1α, such as antisense or siRNA, induced apoptosis of human tongue squamous carcinoma cells in vitro and inhibited tumour growth in human cervical and colon adenocarcinoma cells in vivo." (PMID 18854835, 2008). "Further bioinformatics analysis identified a possible interaction between HIF-1α and TRAF6, an upstream effector of the NF-κB pathway that was confirmed by coimmunoprecipitation in MC-38 and CT26 colon adenocarcinoma cells and in situ by proximity ligation assay." (PMID 33142239, 2020). "In addition, we observed a negative correlation between Ki67 proliferative indexes and HIF‐1α expression in breast adenocarcinoma metastases to the lung, in line with our findings in experimental colon adenocarcinomas." (PMID 32686360, 2020).
glomerulosclerosis (17 papers, 2017 to 2026). A hardening of the kidney glomerulus caused by scarring of the blood vessels. "In mouse models of diabetic nephropathy, downregulation of HIF1α is associated with improved renal function, reduced proteinuria, and glomerulosclerosis." (PMID 35966094, 2022). "In a mouse podocyte ablation model, HIF1α knockout can alleviate glomerulosclerosis and collagen deposition." (PMID 40661082, 2025). "In our study, HBOT reduced glomerulosclerosis, interstitial inflammation, and fibrosis independently of FN and HIF-1α, indicating that the reduction in the intensity of fibrogenesis is related, at least partly, to the improvement in desmin protein expression." (PMID 39767695, 2024). "Counteracted glomerulosclerosis and interstitial fibrosis by restoring abnormal HIF-1α and HIF-2α expressions." (PMID 38929190, 2024). "Nevertheless, knockout of HIF-1α was protective against glomerulosclerosis and glomerular type-I collagen accumulation in a mouse podocyte ablation model." (PMID 36297636, 2022). "Long-term overactivation of HIF-1α can induce the deposition in the ECM, causing glomerulosclerosis and renal interstitial fibrosis." (PMID 34539795, 2021). "In a glomerulosclerosis model, HIF-1α was shown to form a complex with phophoSMAD3 at the COL1A2 promoter, inducing Col-1 synthesis." (PMID 29603016, 2019). "In a podocyte ablation model, HIF‐1α has been shown to induce glomerulosclerosis through interaction with Smad3 (Baumann, Hayashida, Liang, & Schnaper, 2016)." (PMID 30614190, 2019). "High HIF-1α may promote glomerular scarring, while the knockout of HIF-1α has been shown to be protective against glomerulosclerosis and glomerular type-I collagen accumulation in a mouse model of podocyte-specific HIF-1α ablation." (PMID 35188068, 2022). "HIF-1α deletion prevents glomerulosclerosis in mouse model with podocyte injury." (PMID 36297636, 2022).
infarction (17 papers, 2014 to 2025). A localised pathological necrosis of tissue resulting from obstruction of the blood supply usually by a thrombus, an embolus, or vascular torsion. "While previous studies have directly implicated HIF1a in limiting myocardial infarct sizes during ischemia and reperfusion injury, the relative contributions of HIF1A expressed in different cell types in the heart remain elusive." (PMID 36247475, 2022). "Related studies reported that HIF1α inhibitor reduced the infarction area and improved the cardiac function in MI mice." (PMID 39538146, 2024). "In a qPCR analysis, increased levels of angiopeptin, CXCL12, HIF-1α and miR-132 were found 24 h after cell-based gene delivery, compared to those in untreated animals with infarction and in control animals." (PMID 35646882, 2022). "Cleaved procaspase-3 dominated in the infarction core with very low HIF-1α expression." (PMID 31504040, 2019). "Although myocardial transfection of HIF-1α and co-transplantation of mesenchymal stem cells could decrease the infarct size, and prevent post-infarction remodeling of the heart, but the role of HIF-2α in cell-autonomous VSEL maintenance remains unknown." (PMID 28079892, 2017). "In the present study, the expression pattern of HIF-1α versus that of VEGF and iNOS in human infarction hearts was investigated, to further clarify the expression of iNOS in MI and its possible role as a forensic marker for cardiac oxidative stress." (PMID 32399898, 2020). "Third, the HIF-1α inhibitor, ACF, abolished the protective effects of RIPC on infarction and neurological function." (PMID 32210788, 2020). "In the present study, mRNA expression of iNOS, hypoxia-inducible factor-1α (HIF-1α), and vascular endothelial growth factor (VEGF) was investigated in postmortem human infarction hearts." (PMID 32399898, 2020). "Our previous study has found that leonurine increases HIF-1α and VEGF expression in rats in chronic infarction." (PMID 28634450, 2017). "First, we only detected the infarction area, and HIF-1α expression level up to day 28, therefore, a longer period of time more than day 28 maybe contribute to deep understanding the effect of HIF-1α." (PMID 37986153, 2023). "To assess the angiogenic effect of constitutive HIF-1α expression and MSC transplantation, we measured vascular density in the peri-infarcted (border zone) region adjacent to the infarction and within the infarction region of the left ventricle at four weeks after coronary ligation." (PMID 24507665, 2014). "HIF-1α was significantly increased after MI, and PR39-ADM dramatically increased the expression of HIF-1α compared to that in other groups at 1 week after infarction; no significance was detected among MI groups at 4 weeks." (PMID 28348718, 2017).
metastatic melanoma (17 papers, 2009 to 2025). A melanoma that has spread from its primary site to another anatomic site. "In human metastatic melanoma cells, deficiency of HIF-1α increased TET2 mRNA and protein expression, and ascorbic acid induced TET2 dependent 5 hmC formation." (PMID 29666467, 2018). "Next, we examined HDAC8 and HIF1A expression patterns in normal, primary, and metastatic melanoma samples." (PMID 36831463, 2023). "The persistence of transcription factor HIF-1a at nuclear level in metastatic melanoma has opened other therapeutic possibility." (PMID 32509589, 2020). "Keet al. also described that human metastatic melanoma cells have low miR-33a/b expression and is involved in the regulation of in vivo functions by acting as a tumor suppressor through targeting HIF-1α." (PMID 28141816, 2017). "The aim of this study was to assess the effect of physiological concentrations of AA on the normoxic expression and activity of HIF-1α in WM9 metastatic melanoma cells and to determine the mechanism for its action." (PMID 26547841, 2015). "HIF-1α protein is highly expressed under normoxic conditions in the WM9 human metastatic melanoma cell line." (PMID 19919690, 2009). "Overall the WM9 metastatic melanoma expressed the highest amount of 785 HIF-1α mRNA (~79× higher than normal human melanocytes)." (PMID 19919690, 2009). "Moreover, we observed that migrating cancer cells from primary tumor sites exhibited lower CypD expression and higher HIF1α expression in metastatic melanoma patients, further reinforcing the link between CypD suppression and metastatic potential." (PMID 40701956, 2025). "Importantly, a strong positive correlation between the expression of HIF1A and GJA1 (encoding for HIF-1α and Cx43, respectively) was observed in a large cohort of metastatic melanoma patients (n = 368), described in The Cancer Genome Atlas (TCGA) database." (PMID 33066331, 2020). "Therefore, we determined whether HIF-1α expression in human metastatic melanoma WM9 cells was dependent on activation of ERK1/2 MAPK signaling." (PMID 19919690, 2009). "The addition of ascorbic acid can effectively reduce the amount of stabilized HIF-1α found under normoxic conditions in both vertical growth phase WM1366 and WM9 metastatic melanoma cells." (PMID 26547841, 2015). "Interestingly, our data also suggest that this phenomenon could occur in patients, given the positive correlation of HIF1A and GJA1 expressions observed in metastatic melanoma TCGA dataset." (PMID 33066331, 2020). "However, knockdown of MEK1 and 2 did not decrease the normoxic expression of HIF-1α protein in human metastatic melanoma WM9 cells." (PMID 19919690, 2009). "Overall our data suggest normoxic expression of HIF-1α is not regulated by the ERK1/2 MAPK pathway, at least in the WM9 human metastatic melanoma cell line." (PMID 19919690, 2009).
rectal cancer (17 papers, 2008 to 2025). A primary or metastatic malignant neoplasm that affects the rectum. "To confirm that the induction of HIF-1α in a hyperglycemic environment was the main cause of radiation resistance, we treated rectal cancer with LW6 (an HIF-1α inhibitor) and radiation in a high glucose environment." (PMID 36011045, 2022). "The results confirmed that the high-glycemic environment could induce the overexpression of HIF-1α to cause CCRT tolerance in rectal cancer and suggest that combining HIF-1α inhibitors could reverse radioresistance in a high glucose environment." (PMID 36011045, 2022). "High HIF1A expression is associated with shorter OS in patients diagnosed with CC, HNSC, and rectal cancer." (PMID 38921041, 2024). "It was observed that there were 2.15, 1.21, and 1.85 greater risks of dying in patients diagnosed with CC (A), HNSC (B), and rectal cancer (C), when they express high levels of HIF1A, respectively, compared to patients with low levels of HIF1A expression." (PMID 38921041, 2024). "It was confirmed that inhibiting HIF-1α can increase the efficacy of radiation for hyperglycemic rectal cancer." (PMID 36011045, 2022). "It was reported that OA up-regulated NOX2 expression, which led to the inhibition of HIF-1α expression, thus triggering the inhibition of cell proliferation in several rectal cancer cell lines and inducing G1/S cycle arrest." (PMID 35887090, 2022). "In the hyperglycemic rectal cancer animal model, rectal cancer cells confirmed that radiation exposure reduces apoptosis by overexpressing HIF-1α." (PMID 36011045, 2022). "We further clarified the effects of the hyperglycemic environment and HIF-1α expression on CCRT resistance in rectal cancers." (PMID 36011045, 2022). "In the future, perhaps HIF-1α inhibitors can be used as CCRT sensitizers in patients with hyperglycemic rectal cancer." (PMID 36011045, 2022). "Further, we analyzed the combined HIF-1α inhibitor with radiation therapy in hyperglycemic rectal cancers." (PMID 36011045, 2022). "Methods and Materials: We analyzed the correlation between prognosis indexes with hypoxia-inducible factor-1 alpha (HIF-1α) in rectal cancer patients with preoperative CCRT." (PMID 36011045, 2022). "To understand the correlation therapeutic efficacy of radiation with HIF-1α level in rectal cancer, we analyzed the expressed HIF-1α level and apoptosis in HCT116 or SW480, respectively." (PMID 36011045, 2022). "Further, elevated ROS mediated by NOX2 upregulated the expression of HIF-1α in the small intestine and rectal cancer cells, contributing to rectal cancer cell proliferation." (PMID 33542787, 2021). "hypoxia-inducible factor-1α and -2α were expressed in >50% of rectal cancers (HIF-1α, 54%, 48/90; HIF-2α, 64%, 58/90)." (PMID 19436307, 2009). "Previous studies suggest that HIF-1α positivity was associated with both TNM stage and vascular invasion in rectal cancer." (PMID 20003271, 2009). "We have also shown a strong correlation between HIF-1α expression and cancer-specific mortality and tumour recurrence suggesting that this factor is an integral component of rectal cancer growth." (PMID 19436307, 2009). "In future, HIF-1α inhibitors might be used as sensitizers to improve the efficacy of hyperglycemic rectal cancer patients receiving CCRT." (PMID 36011045, 2022). "We detected the HIF-1α activation pathway of rectal cancer cells in different glucose concentrations and investigated whether the environment could affect the sensitivity of rectal cancer cells to 5-FU or radiation." (PMID 36011045, 2022). "In the future, it may be possible to use HIF-1α inhibitors to target CCRT in hyperglycemic rectal cancer patients." (PMID 36011045, 2022). "HIF-1α inhibitors may be useful for development as CCRT sensitizers in patients with hyperglycemic rectal cancer." (PMID 36011045, 2022). "In this study, we confirmed that LW6 is an HIF-1α inhibitor for hyperglycemic rectal cancer." (PMID 36011045, 2022).
rectal cancer (continued). "In addition, we confirmed that a high glucose environment could induce the GLUT1-OGT-HIF-1α signaling pathway to promote 5FU-resistance and radioresistance of rectal cancer cells by overexpressing HIF-1α." (PMID 36011045, 2022). "Therefore, HIF-1α is a key CCRT resistance factor in hyperglycemic rectal cancer." (PMID 36011045, 2022). "The data showed high levels of HIF-1α expression in 17 (31.5%) and low levels in 37 (68.5%) of 54 pre-CCRT rectal cancer cases." (PMID 36011045, 2022). "Our study comprises one of the largest groups of rectal cancer cases across all stages and we have determined that both HIF-1α and HIF-2α were widely expressed in rectal cancer compared with normal large bowel mucosa (controls)." (PMID 19436307, 2009). "In the present study we focused on the clinical and prognostic implications of the expression of HIF-1α and VEGF in patients with CRC, not only rectal cancer." (PMID 20003271, 2009). "Using one of the largest cohorts of rectal adenocarcinomas to date, this study investigated hypoxia-inducible factor-1α (HIF-1α) and HIF-2α protein expression in relation to rectal cancer recurrence and cancer-specific survival." (PMID 19436307, 2009). "To further establish the value of pharmacological inhibition of HIF-1α in increasing 5-FU sensitivity, we selected a patient with rectal cancer (male, Dukes’ C) who did not respond to 5-FU-based preoperative neoadjuvant chemotherapy." (PMID 34998404, 2022). "Therefore, the gene expression levels of four genes, HIF1A, MTHFD1, GGH and TYMS, in tumor tissues before CRT may be useful for predicting the efficacy of preoperative CRT including S-1 or UFT/LV in patients with rectal cancer." (PMID 28417167, 2017). "It has been established that the miRNA-24/VHL/HIF-1α double negative feedback network enhances HIF-1α expression, enhancing the survival and growth of rectal cancer cells." (PMID 40506042, 2025).
age-related macular degeneration (16 papers, 2016 to 2024). Age-related loss of vision in the central portion of the retina (macula), secondary to retinal degeneration. "Such in vivo suppression of upregulated expression of angiogenesis-related genes by pharmacological inhibitors of HIF-1α suggests a new potential approach to the treatment of age-related macular degeneration." (PMID 38691000, 2024). "Previous studies have demonstrated therapeutic effects on age-related macular degeneration by inhibiting Hif-1α." (PMID 38132462, 2023). "Some authors also checked the association of the HIF1A gene with cellulite, hemodialysis patients, high-altitude polycythemia (HAPC), and age-related macular degeneration (AMD)." (PMID 35972942, 2022). "Furthermore, studies have indicated that HCA can inhibit choroidal neovascularization through suppression of hypoxia-inducible factor-1 alpha (HIF-1α) in the treatment for age-related macular degeneration." (PMID 38132462, 2023). "It was recently proposed that chronic hypoxia may develop in the physiologically aging retina and that age-related macular degeneration is induced by the subsequent increased activity of HIF1α- and HIF1α-targeted genes." (PMID 35123567, 2022). "Another study, which was related to the incidence of hypoxia, showed that administration of nanoparticle polymers containing DOX could inhibit HIF-1α activity in patients with Age-related macular degeneration (AMD)." (PMID 35340325, 2022). "Furthermore, they tested the therapeutic potential of CjCas9 by targeting the Vegfa or Hif1a genes, genes associated with choroidal neovascularization (CNV) and age-related macular degeneration (AMD) in mice." (PMID 30621179, 2019). "Likewise, intravitreal delivery of AAVs carrying CjCas9 and LbCpf1 successfully disrupted angiogenesis-associated genes Vegfa and Hif1a in the mouse retina, which substantially decreased the excessive choroidal neovascularization in a transgenic model for age-related macular degeneration (AMD)." (PMID 33594520, 2021). "Furthermore, CjCas9 targeted to the Vegfa or Hif1a gene in RPE cells reduces the size of laser-induced choroidal neovascularization, suggesting that in vivo genome editing with CjCas9 is a new option for the treatment of age-related macular degeneration." (PMID 28220790, 2017). "However, by making capsules containing polylactic coglycolic acid (PLGA) and chitosan (NanoDOX) it can suppress the expression of HIF-1α and VEGF in patients with Age-related Macular Degeneration (AMD)." (PMID 35340325, 2022).